CDK4 (cyclin dependent kinase 4)
Diseases named in the same sentence as CDK4 in open-access papers (continued):
Sharing a sentence is not in itself a finding about the gene and the disease.
tumor (continued). "Using strains of genetically modified mice, genetic studies have provided direct evidence for the role of CDK4 in tumor development." (PMID 26528855, 2015). "It has been reported that the efficacy of CDK4 inhibitors requires that the tumor cell express a normally functioning pRb." (PMID 26528855, 2015). "CDK4 inhibitor p16INK4 showed upregulation in the tumor (P < 0.001) and adjacent normal tissues (P < 0.001) as well as in the Cs group (P = 0.007) but remained same in the NDMA group." (PMID 26313366, 2015). "Recently, clinical studies have demonstrated that CDK4/6 inhibitors can have potent single agent activity in select tumor models ostensibly addicted to kinase activity, such as liposarcoma and mantle cell lymphoma." (PMID 25156567, 2014). "Second, while the median levels of MDM2 and CDK4 expression were higher in ALT/WDL, the overlapping range of values for each tumor type is a limitation to the diagnostic usefulness of this test." (PMID 24965044, 2014). "Intermediary proteins in the RB tumor suppressor pathway, Cdk4 and p16Ink4a, govern critical checkpoints that monitor cellular aging, senescence, immortalization capacity and transformation potential." (PMID 25352948, 2014). "CAPE and CAPPE further significantly inhibited the expression of FASN, cyclin D1, cyclin E, Cdk4 and c-myc proteins of tumor tissues in an in vivo animal study." (PMID 24960186, 2014). "In this investigation, we observed that p15 and p16, two tumor suppressors that are upstream regulators of CDK4 were positively modulated by let-7c, whereas CDK4 and E2F1 were negatively regulated by let-7c in NPC cells." (PMID 24751144, 2014). "It was noteworthy that the effects of altered cdk4 expression in normal mammary epithelial cells was similar to that seen in the tumor cell lines with respect to AKR1C-family proteins but differed with respect to others SMEs." (PMID 24848372, 2014). "The widely accepted model of G1 cell cycle progression proposes that cyclin D:Cdk4/6 inactivates the Rb tumor suppressor during early G1 phase by progressive multi-phosphorylation, termed hypo-phosphorylation, to release E2F transcription factors." (PMID 24876129, 2014). "Here, we report the identification of LY2835219, a potent inhibitor of CDK4/6 that inhibits phosphorylation of Rb and induces a G1 cell cycle arrest in Rb-proficient tumor cells in vitro." (PMID 24919854, 2014). "We describe the identification and preclinical characterization of LY2835219, a potent inhibitor of CDK4/6 with antiproliferative activity in a variety of tumor models in vitro and in vivo." (PMID 24919854, 2014). "We examined four disparate human tumor cell lines that express wild-type Rb, and are deleted for the p16 tumor suppressor gene, a specific inhibitor of Cdk4/6." (PMID 24876129, 2014). "Fascaplysin, the natural product of a marine sponge, exhibits anticancer activity against a broad range of tumor cells, presumably through interaction with DNA, and/or as a highly selective cyclin-dependent kinase 4 (CDK4) inhibitor." (PMID 24608973, 2014). "In this study, we examined the expression of tumor-suppressive miRNA let-7c by qPCR in NPC cells after knockdown of CDK4." (PMID 24751144, 2014). "The CDK4 inhibitor P276, in combination with gemcitabine, inhibited tumor growth and angiogenesis of pancreatic cancer cell xenografts in nude mice." (PMID 25349887, 2014). "Cdk4 inhibition and p19 increase has recently been demonstrated to drive tumor cells into the S-phase." (PMID 25136960, 2014). "The protein levels of Cyclin E1, Cyclin D3, Cyclin D1,Cyclin A2, CDK2 and CDK4 were significantly decreased in tumor tissues harvested from miR-188 injected mice." (PMID 25304455, 2014).
tumor (continued). "Further, we found that reduced CDK4 expression elevated the expression of let-7c, a tumor-suppressive miRNA modulated by E2F1." (PMID 24751144, 2014). "These agents were synergistic with CDK4/6 inhibition, blocked the aberrant upregulation of Cyclin E1, and yielded potent inhibition of tumor cell growth." (PMID 25156567, 2014). "Several studies have demonstrated the contribution of Cdk4 in tumor development in brain, skin, pancreas, eye, and tooth." (PMID 23530816, 2013). "In contrast, all cell lines harboring CDK4 knockdown, including ER-PR-HER2+, ER-PR-HER2-, and MCF10A showed significantly decreased IC50, meaning that the ablation of CDK4 in both the normal and tumor cell lines sensitizes these cells to radiation." (PMID 23886499, 2013). "The p16 protein exerts a tumor suppressor function by binding to the cyclin D1 CDK4/CDK6 complex, preventing the phosphorylation of the retinoblastoma (Rb) protein and resulting in G1 arrest." (PMID 24319475, 2013). "Despite constitutive cyclin D expression, defective expression of INK4 CDK4/6 inhibitory proteins and frequent overexpression of cyclin E, many tumor cells maintain at least partial regulation at the R point." (PMID 23737759, 2013). "CDK4 inhibition would thus restore native cell cycle regulation and prevent uncontrolled tumor cell proliferation." (PMID 24216990, 2013). "The observation that a decreased p16INK4a level, which leads to increased activation of Cdk4, correlates with PAX3-FOXO1 expression in ARMS tumor formation would predict that pharmacologic inhibition of Cdk4 is effective for treating ARMS." (PMID 23469153, 2013). "A tendency for CKD4 positivity to correlate with a higher tumor grade was noticed, however, coinciding with the notion that CDK4 promotes tumor cell proliferation." (PMID 23336272, 2013). "The average length of the transcripts that are overexpressed in the tumor only (including, e.g., the transcript of the human gene CDK4), is greater than that of the transcripts that are overexpressed in both the normal and tumor." (PMID 24282503, 2013). "The transcriptomic analysis revealed marked downregulation of the RB tumor suppressor pathway with major players such as cyclin D1, CDK4, and E2F mRNAs strongly suppressed." (PMID 23902736, 2013). "The p16INK4a transgene dramatically delayed mammary tumorigenesis by ErbB2, indicating that ErbB2-mediated deregulation of cyclin D1/Cdk4/6 is a crucial step of tumor formation." (PMID 24205004, 2013). "The expected mechanism-based increase in HSP72 expression was observed in all 3 treated tumours, and a decrease in the expression of NEU/HER2, C-RAF and CDK4 was seen in 2 out of 3 tumours." (PMID 22621282, 2012). "In most cases, the contribution of CDK6 to tumor phenotypes has been assessed in conjunction with CDK4, particularly in studies using PD332991 which inhibits both kinases." (PMID 23300567, 2012). "This and other oncogenic client proteins (e.g. B-RAF, C-RAF, ALK and CDK4) are depleted by 17-AAG in both animal tumours and patients." (PMID 22621282, 2012). "We observed a striking decrease in the levels of PCNA, cyclin B1 and CDK4 levels and increase in the levels of tumor suppressor E-cadherin and pro-apoptotic protein Bim in the tumor tissue lysates of RLIP76 antisense-treated mice as compared with controls." (PMID 22509328, 2012). "Western blots for HSP72, NEU/HER2, C-RAF and CDK4 were carried out on tumours from a cohort of 3 control mice and 3 mice treated with 40mg/kg of 17-AAG for 3 days, where tumours were excised 24 hours after the last dose." (PMID 22621282, 2012).
tumor (continued). "TAGCNA identifies SCEs that are known to be involved with proto-oncogenes (e.g. EGFR, CDK4) and tumor suppressor genes (e.g. CDKN2A, CDKN2B), and provides many additional SCEs with potential biological relevance in these data." (PMID 22815924, 2012). "It is believed that such destabilization of client proteins (like raf, Src, Lck, Wee1, Mek, Cdk4, Src, Ck2, Akt, ErbB2 etc.)is responsible for the anti-mitotic and anti-tumor activity of the drug." (PMID 22361388, 2012). "The p16ink4a gene is a tumor suppressor that acts as a negative regulator of the cell cycle by binding to and inhibiting cyclin-dependent kinase 4 (CDK4)." (PMID 22235214, 2011). "In the majority of cases, however, other genetic and epigenetic changes lead to increases in CDK4/6 activity contributing to tumour cell growth." (PMID 21610706, 2011). "In our patient, IHC and FISH analyses for MDM2 and CDK4 were done on 2006 from paraffin-embedded tumour samples biopsied on 2004." (PMID 21106072, 2010). "Examination of 37 paired tissues of NSCLC tumors and adjacent uninvolved lung, and the NSCLC cell lines for c-Myc, eIF4E and CDK4 expression showed enhanced levels in tumor tissues and cancer cell lines." (PMID 21092188, 2010). "P16INK4A is a critical member of the Rb/p16 tumor-suppressor pathway which inhibits the activation of cdk4/6, preventing the progression through the cell cycle." (PMID 20604950, 2010). "80% of human tumors show a deregulation of the cell cycle relevant Cdk4-cyclin D1/retinoblastoma (pRb)/E2F signal cascade resulting in uncontrolled tumor growth." (PMID 20428073, 2010). "Tumour suppressor CDKN2A inhibits the cyclin-dependent kinases (Cdk4 and Cdk6) that initiate the phosphorylation of the pRb." (PMID 20842131, 2010). "CDKN2A (also known as p16-INK4A) is a tumor suppressor that binds to the complex of cyclin D1 and cyclin-dependent kinase 4 to repress its ability to phosphorylate the retinoblastoma protein, and consequently, blocks cell cycle progression from G1 to S." (PMID 20465802, 2010). "Two 124I-labeled cyclin-dependent kinase 4/6 inhibitors were developed to study the role of Cdk4/6 during cell proliferation in tumor cells." (PMID 20428073, 2010). "Radiolabeled Cdk4 inhibitors have been suggested as promising molecular probes for imaging tumor cell proliferation." (PMID 20428073, 2010). "P16INK4A is a critical member of the Rb tumor-suppressor pathway which acts to arrest the cell-cycle at G1/S by inhibiting the binding of cdk4/6 to Cyclin D1 and subsequently inhibiting the phosphorylation of Rb." (PMID 20604950, 2010). "The inactivation of the CDKN2A gene, which encodes an inhibitor of CDK4 and CDK6, is one of the most common molecular events in human neoplasms." (PMID 22933911, 2010). "In fact, previous results from our group showed that activated p110α transgenic expression in CDK4(R24C) mutant background produces an increase in preneoplastic lesions and in tumor formation." (PMID 20174572, 2010). "The question to be answered is, if exceeding high selectivity of pyrido[2,3-d]pyrimidin-7-one derivatives against other Cdks than Cdk4 will be of outstanding importance for tumor treatment." (PMID 19551155, 2009). "In summary, CKIA and also the new compound CKIB were demonstrated to act as tumor cell growth inhibitors via specific inhibition of Cdk4-Cyclin D/pRb/E2F signaling pathway." (PMID 19551155, 2009). "They encode inhibitors of the genes CDK4/CDK6 and are believed to play critical roles in cell proliferation and tumor suppression." (PMID 19214202, 2009). "Specific inhibition of Cdk4-cyclin D results in pRb hypophosphorylation which prevents cell proliferation and further tumor growth." (PMID 19551155, 2009). "In this study, we have focused on cyclin-dependent kinase 4 (Cdk4), a key molecule in the regulation of cell cycle progression at the G1-S phase restriction point and p16INK4a, a tumor suppressor which inhibits Cdk4 activity." (PMID 19352455, 2009).
tumor (continued). "In fact, incubation of RCC cells with thiazolidinedione decreased the protein levels of cyclin D1 and cdk4, and increased the levels of p27 which altogether led to G0/G1 arrest and massive tumor cell apoptosis." (PMID 19473483, 2009). "The loss of RB1 is also a well-characterised occurrence in many other human tumour types and it is probable that the p16INK4a-CDK4/6-RB pathway is disrupted in most human tumours." (PMID 18782450, 2008). "Recent evidence links nuclear retention of active cyclin D1/CDK4 complexes with genomic instability, providing a novel mechanism wherein cyclin D1 stabilization initiates tumor formation." (PMID 18764945, 2008). "Given the phenotypic outcome of accumulated nuclear cyclin D1/CDK4 complexes, further mechanistic investigation is required for development of novel therapeutic strategies to promote tumor cell death in cancers overexpressing cyclin D1." (PMID 18764945, 2008). "Our study shows a stepwise increase in the expression level of CDK4 from normal to tumor tissues indicating an important role for CDK4 at an early stage of transformation of HPV- infected cervical epithelium." (PMID 17521451, 2007). "To answer this question, we have to determine if Rb wild type cancer cells require Cdk2 and Cdk4 activities throughout tumor progression." (PMID 16759374, 2006). "Altered genes in high-grade tumours were related to cell cycle (cyclin-dependent kinase 4) and transcription (jun d proto-oncogene)." (PMID 16265353, 2005). "In a univariate analysis, the prognosis of patients with tumours that were both cyclin D1- and CDK4-positive was significantly poorer than that of patients with cyclin D1-negative tumours (P < 0.05)." (PMID 10390005, 1999). "Thirty-nine tumours (43.3%) and 31 tumours (34.4%) exhibited both cytoplasmic and nuclear positivity for CDK4 and CDK2 respectively." (PMID 10390005, 1999). "Of 28 cyclin D1-positive and 27 cyclin E-positive tumours, CDK4 was overexpressed in 12 (42.8%) tumours and CDK2 in seven (25.9%) tumours respectively." (PMID 10390005, 1999). "In the same experiment CDK4 protein was found homogeneously expressed in all the tumour specimens and in the five cell lines." (PMID 9231912, 1997). "As the p16 protein is involved in a cell cycle regulatory pathway consisting of at least pRb, cdk4 and cyclin D1, the tumours were also screened for amplifications of the last two genes." (PMID 8611425, 1996). "The level of CDK4 mRNA expression was increased in nine tumours in addition to the 12 samples with CDK4 amplification." (PMID 7640224, 1995). "Homozygous deletions of the putative tumour-suppressor gene CDKN2, which encodes an inhibitor of cdk4, have been detected in a high percentage of cancer cell lines of various histological types." (PMID 7640224, 1995). "Notably, FGFR signaling induces epigenetic suppression of cell cycle inhibitors, enabling tumor cell survival despite CDK4/6 blockade." (PMID 40421216, 2025). "The mechanism of action is based on inhibiting the phosphorylation of tumor-suppressor retinoblastoma protein by preventing CDK4/6 from binding to cyclin D. This effectively inhibits tumor cell proliferation, and delay or even overcome the development of endocrine resistance." (PMID 41008856, 2025). "A previous review has summarized in detail the role of CDK4 in tumor cells." (PMID 40486867, 2025). "It is recognized that CDK4/6is can induce tumor cell cycle arrest." (PMID 41463246, 2025). "Moreover, recent studies suggest that CDK4/6 inhibition can reverse the immune-refractory phenotype of certain tumour cells." (PMID 41388212, 2025).
tumor (continued). "The additional losses of CDK4, chromosome 13 and the X‐chromosome suggest tumor progression that could influence its biological behavior as well as the potential for further metastasis." (PMID 41225763, 2025). "Collectively, our findings underscore the tumor‐promoting function of the CDK4/6‐DUB3 axis in CRC through stabilizing YAP, suggesting that CDK4/6 inhibitors could be promising for CRC associated with aberrantly elevated DUB3 and YAP1." (PMID 39968498, 2025). "Interestingly, CDK4/6i treatment has been found to enhance anti-tumor immunity by suppressing regulatory T cells (Tregs) and promoting cytotoxic T-cell activity." (PMID 40703657, 2025). "To test whether enhancing BBB glial cell cycle progression could promote tumor growth under NR, we overexpressed the cell cycle genes Cdk4 and CycD using the GMR85G01-GAL4 driver." (PMID 41252380, 2025). "CDK4/6is-induced cellular senescence plays a dual role in tumor immunity." (PMID 41463246, 2025). "The addition of cyclin-dependent kinase 4/6 (CDK4/6) inhibition may enhance the durability of anti-tumor responses, offering a potential chemotherapy-sparing alternative, although its role in the frontline setting remains uncertain." (PMID 40743286, 2025). "Concurrent PD-L1 upregulation by CDK4/6 inhibitors further complicates this interplay, suggesting that immune checkpoint blockade may counteract resistance by leveraging heightened tumor immunogenicity." (PMID 40421216, 2025). "Moreover, CDK4/6 plays a critical role beyond its canonical function in cell cycle regulation, influencing various biological processes, including apoptosis, tumor growth, metastasis, and immunogenicity." (PMID 39968498, 2025). "This process may further suppress CD8+ T cell infiltration by activating downstream cascades such as CDK4/6 activation, facilitating tumor immune escape." (PMID 41019083, 2025). "An in vivo study investigating the RANK pathway and CDK4/6 inhibition indicated that RANK pathway inhibition can modulate immune responses, thereby influencing the tumor microenvironment and potentially synergizing with the antitumor activity of CDK4/6 inhibitors." (PMID 40005476, 2025). "Moreover, abemaciclib, a CDK4/6 inhibitor, primes lysosome activation and promotes lysosomal degradation of B7-H4 independently of the tumor cell cycle." (PMID 40341398, 2025). "Additional evaluation in immune-deficient xenograft models reproduced the synergistic anti-tumor efficacy of the combined inhibition of CDK4/6 and MEK, unlike the vehicle and single-agent controls." (PMID 40723291, 2025). "Given that the interferon response is often associated with robust immune infiltrates, there is growing evidence suggesting that CDK4/6 inhibitors can synergize with immune checkpoint inhibitors (ICIs) to enhance anti-tumor immunity and improve therapeutic outcomes." (PMID 41326426, 2025). "Thus, future studies need to identify the optimal CDK4/6i-based combinations and timing with other targeted therapies to effectively modulate the tumor immune microenvironment to promote tumor killing." (PMID 40282469, 2025). "Abemaciclib targets CDK4/6 to mediate anti-tumor activities in clinical and preclinical settings." (PMID 40341398, 2025). "Currently, the application of CDK4/6is in anti-tumor immunotherapy remains a controversial topic." (PMID 41463246, 2025). "In HCC patients, CDK4 has been observed to be significantly expressed and linked to a number of advanced clinical characteristics (OS event, T-stage histologic grade, tumor status), implying that CDK4 needs additional clinical validation as a possible prognostic and diagnostic marker." (PMID 38231074, 2025). "However, CDK4/6is suppress anti-tumor immunity through aberrant activation of the interferon signaling pathway and increased expression of PD-L1 in tumor cells." (PMID 41463246, 2025).